KSR1 (kinase suppressor of ras 1)
Description:
Part of a multiprotein signaling complex which promotes phosphorylation of Raf family members and activation of downstream MAP kinases (By similarity). Independently of its kinase activity, acts as MAP2K1/MEK1 and MAP2K2/MEK2-dependent allosteric activator of BRAF; upon binding to MAP2K1/MEK1 or MAP2K2/MEK2, dimerizes with BRAF and promotes BRAF-mediated phosphorylation of MAP2K1/MEK1 and/or MAP2K2/MEK2. Promotes activation of MAPK1 and/or MAPK3, both in response to EGF and to cAMP (By similarity). Its kinase activity is unsure (By similarity). Some protein kinase activity has been detected in vitro, however the physiological relevance of this activity is unknown (By similarity).
Synonyms: KSR; RSU2
Tractability: Small molecule: a structure with a bound ligand is known; a high-quality ligand is known; it belongs to a druggable protein family. Antibody: UniProt places it where antibodies can reach, with high confidence; its Gene Ontology location is reachable by antibodies, with medium confidence. PROTAC: ubiquitination databases record sites on it; its protein half-life has been measured; a small molecule that binds it is known.
Target class: Protein Kinase; TKL protein kinase group; Kinase; Enzyme
Gene: Protein-coding gene on chromosome 17 (27,456,448 to 27,626,438, forward strand). Ensembl gene ENSG00000141068.
Subcellular location: Cytoplasm; Membrane; Cell membrane; Cell projection, ruffle membrane; Endoplasmic reticulum membrane
Subcellular location (Human Protein Atlas): Cytosol; Vesicles
Pathways (Reactome):
Disease: Paradoxical activation of RAF signaling by kinase inactive BRAF; Signaling by BRAF and RAF1 fusions; Signaling by RAF1 mutants; Signaling by high-kinase activity BRAF mutants; Signaling by moderate kinase activity BRAF mutants; Signaling downstream of RAS mutants
Signal Transduction: MAP2K and MAPK activation; Negative regulation of MAPK pathway; RAF activation
Gene Ontology:
Molecular function: 14-3-3 protein binding; ATP binding; protein binding; MAP-kinase scaffold activity; protein serine kinase activity; protein kinase activity; protein serine/threonine kinase activity
Biological process: positive regulation of MAPK cascade; Ras protein signal transduction; regulation of cell population proliferation; regulation of MAP kinase activity; MAPK cascade
Cellular component: cytoplasm; cytosol; endoplasmic reticulum; endoplasmic reticulum membrane; membrane; protein-containing complex; plasma membrane; ruffle membrane
Genetic constraint (gnomAD): Loss-of-function variants: 27 observed, 77.47 expected, observed/expected ratio (o/e) 0.35, 90% interval 0.26 to 0.48. The upper end of that interval is the gene's LOEUF score, 0.48, which puts it in group 2 of 6, group 1 being the genes least tolerant of losing a copy. Missense variants: 832 observed, 1,006 expected, observed/expected ratio (o/e) 0.83, 90% interval 0.78 to 0.88. Synonymous variants: 420 observed, 408.27 expected, observed/expected ratio (o/e) 1.03, 90% interval 0.95 to 1.12.
Homologues: Orthologues: chimpanzee KSR1 (94% identical), pig KSR1 (94% identical), dog KSR1 (93% identical), rat Ksr1 (91% identical), guinea pig KSR1 (88% identical), mouse Ksr1 (86% identical), rabbit KSR1 (85% identical), macaque KSR1 (79% identical), tropical clawed frog ksr1 (68% identical), zebrafish ksr1a (61% identical), zebrafish ksr1b (56% identical). Paralogues in human: KSR2 (49% identical), BRAF (16% identical), LRRK2 (15% identical), RAF1 (14% identical), ARAF (14% identical), TNNI3K (13% identical), LIMK1 (12% identical), MAP3K10 (12% identical), MAP3K9 (12% identical), MAP3K21 (12% identical), MAP3K11 (11% identical), LIMK2 (11% identical), and 11 more.
Diseases named in the same sentence as KSR1 in open-access papers:
KSR1 is named in the same sentence as 58 diseases in open-access papers, as found by Europe PMC text mining. Sharing a sentence is not in itself a finding about the gene and the disease. The quoted sentences say what the papers report.
breast carcinoma (10 papers, 2014 to 2025). "However, our own studies reveal an interesting, and yet unexpected role of KSR1 in breast cancer, where Ras mutations are rare." (PMID 26425651, 2015). "Next, we evaluated the association between endogenous KSR1 and MST1 in MCF-7 breast carcinoma cells." (PMID 41326667, 2025). "Following these results, we searched the available databases in order to analyze in further depth how KSR1 levels influenced the clinical evolution of breast cancer patients." (PMID 39263917, 2025). "Noticeably, cells expressing high levels of Nm23‐H1 exhibit a pronounced KSR1 degradation, suggestive of a correlation between KSR1 levels and an adverse evolution of mammary cancer patients, as our findings related to clinical data demonstrate." (PMID 39263917, 2025). "Overall, our results portray both ERK dimerization and KSR1 as essential factors for the regulation of cell motility and mammary tumor dissemination." (PMID 39263917, 2025). "In agreement, clinical data disclose that high KSR1 expression levels correlate with greater metastatic potential and adverse evolution of mammary tumors." (PMID 39263917, 2025). "Recent studies have shown that KSR1 is expressed in many tumor cell lines, such as lung cancer, prostate cancer, breast cancer and so on, and the expression of KSR1 is related to the sensitivity of antineoplastic drugs." (PMID 33461174, 2021). "In a study of human breast cancer where RAS mutations are rare, high KSR1 levels were shown to correlate with overall survival, and mechanistic studies suggested that this is due to KSR1 stabilization of BRCA1." (PMID 29596465, 2018). "Previously, we showed that KSR1 deficiency attenuated both the number and the growth of tumors that developed using the MMTV breast cancer model." (PMID 29596465, 2018). "Of note, breast cancer cells overexpressing KSR1 form fewer and smaller size colonies compared to the parental ones, while an in vivo mouse model also demonstrates that the growth of xenograft tumors overexpressing KSR1 is inhibited." (PMID 26425651, 2015). "Similarly, KSR1 knockout mice displayed a significant reduction in mammary tumor burden in models expressing the polyomavirus middle T antigen, indicating the in vivo tumor-promoting function of KSR1." (PMID 41155983, 2025). "Since our data implicated KSR1 in the regulation of cellular motility of mammary cells, we sought to gain an insight into the clinical relevance of this finding, by analyzing KSR1 levels in a TMA made up of 51 PDXs coming both from primary mammary tumors and metastases." (PMID 39263917, 2025). "KSR1, which tightly regulates MAPK/ERK signaling output, has been shown to be overexpressed in endometrial and colon carcinoma and high expression levels reported to be associated with decreased survival in breast cancer." (PMID 28732488, 2017). "Our current understanding of KSR1's function in breast cancer is far from complete." (PMID 26425651, 2015). "KSR1 expression is positively associated with breast cancer 1, early onset (BRCA1), BRCA1-associated ring domain 1 (BARD1) and checkpoint kinase 1 (Chk1) levels in breast cancer specimens." (PMID 26425651, 2015). "Data corresponding to 6344 breast cancer cases included in five different repositories, revealed that 4% of these cases exhibited genetic alterations in the KSR1 locus, amplifications almost in every case, which, conceivably, should result in augmented KSR1 levels." (PMID 39263917, 2025). "In the human breast carcinoma cell line MDA-MB435 and in HEK293 cells NM23-H1 has been shown to phosphorylate KSR1 on Ser392, and NM23-H1 overexpression in those cells resulted in reduced levels of MAPK signaling." (PMID 24829611, 2014). "To verify our findings in another cell type and to investigate whether KSR1 regulates YAP activity in breast epithelium, we used siRNA to knock down KSR1 in MCF-7 human breast carcinoma cells that constitutively express a TEAD-responsive luciferase reporter." (PMID 41326667, 2025).
breast carcinoma (continued). "In a mouse model of breast cancer based on a viral oncogene, the absence of KSR1 results in reduced tumor frequency and progression." (PMID 29596465, 2018). "In breast cancer, higher KSR1 expression correlated with improved patient survival, suggesting that in specific tumor settings, KSR1 may attenuate rather than enhance oncogenic RAS/MAPK signaling." (PMID 41155983, 2025).
colorectal cancer (6 papers, 2017 to 2025). A primary or metastatic malignant neoplasm that affects the colon or rectum. "Although KSR1 is dispensable for normal development, it is necessary for oncogenic Ras-induced tumorigenesis including colorectal cancer cells, suggesting that KSR1 may modulate aberrant signals that redirect the function of effectors typically involved in normal cellular homeostasis." (PMID 33970103, 2021). "Another inhibitor of ERK1/2 is the oncosuppressor Erbin, which interacts with the kinase suppressor of Ras-1 (KSR1) and down-regulates the RAS/RAF/MEK/ERK1/2 pathway in colorectal cancer." (PMID 31117237, 2019). "Reduced KSR1 and AMPK expression also downregulated expression of PGC1β and ERRα, which inhibits the survival of colorectal cancer cells." (PMID 29121859, 2017).
gastric cancer (6 papers, 2021 to 2024). A primary or metastatic malignant neoplasm involving the stomach. "When Liu and colleagues used EGb 761 in stomach cancer cells, they observed similar effects; however, the underlying mechanisms of EGb 761 activity were restricted to the kinase suppressor of Ras 1 (KSR1)-mediated extracellular signal-regulated kinase (ERK) 1/2 pathway." (PMID 35265150, 2022). "In gastric cancer cells and tumor associated macrophages, ELK4 might possibly activate lysine-specific demethylase 5A (KDM5A), which inhibits the expression of Praja 2 (PJA2), thus decreasing kinase suppressor of Ras 1 (KSR1)." (PMID 37381723, 2023). "In gastric cancer, ELK4 plays a role in regulating the lysine-specific demethylase 5 (KDM5A)/Praja-2 (PJA2)/kinase suppressor of RAS1 (KSR1) axis." (PMID 37381723, 2023). "We tried to elaborate the molecular mechanism of ETS-like transcription factor 4 (ELK4) affecting gastric cancer (GC) progression through M2 polarization of macrophages mediated by lysine-specific demethylase 5A (KDM5A)-Praja2 (PJA2)-kinase suppressor of ras 1 (KSR1) axis." (PMID 34372882, 2021).
colon carcinoma (4 papers, 2017 to 2021). "To determine the effect of KSR1 on translatomes in colon cancer cells, we performed genome-wide polysome profiling." (PMID 33970103, 2021). "We sought to determine the functional relevance of KSR1-dependent induction of EPSTI1 to phenotypic plasticity in colon cancer cells." (PMID 33970103, 2021). "Cell viability was also markedly reliant on TIMELESS expression in colon cancer cells compared to HCECs, similar to that of KSR1." (PMID 33120942, 2020). "In contrast, KSR1 or EPHB4 knockdown significantly decreased cell viability in colon cancer cell lines HCT116 and Caco2 compared to the control siRNA." (PMID 33120942, 2020). "But it is unknown which proteins KSR1 helps synthesize and whether it plays a role in the metastasis of colon cancer cells." (PMID 33970103, 2021). "The experiment showed that KSR1 increases the levels of a protein called EPSTI1, which colon cancer cells need to transform into migratory cells." (PMID 33970103, 2021). "To determine the extent to which KSR1- and ERK-dependent EPSTI1 translation is critical to colon tumor cell growth and invasion, we expressed a MSCV-FLAG-EPSTI1-GFP construct in KSR1-CRISPR knockout HCT116, SW480, and HCT15 cells." (PMID 33970103, 2021). "Silencing of Erbin, a tumor suppresser known to disrupt KSR1-RAF1 interaction, promoted cell migration and invasion of colon cancer cells, but did not identify the mechanism on how KSR1-dependent MAPK signaling affected EMT." (PMID 33970103, 2021). "We showed previously that KSR1 expression is upregulated in colon cancer cell lines when compared to the non-transformed human colon epithelial cells (HCECs)." (PMID 33970103, 2021).
Obesity (4 papers, 2017 to 2023). Accumulation of substantial excess body fat. "Collectively, these data indicate that KSR1 modulation may have therapeutic potential for diseases driven by NT gene expression and peptide secretion, such as obesity-associated metabolic disorders and Ras-driven cancers." (PMID 30917119, 2019). "Kinase suppressor of Ras 1 has been reported to attenuate neurostatin secretion and extracellular signal-regulated kinase 1 and 2 signaling in human endocrine cells, thereby participating in obesity-related metabolic disorders and Ras-driven cancer." (PMID 36816960, 2023). "KSR1 has been reported to be related to the regulation of glucose homeostasis, and GTF3C3- to obesity-related dysglycaemia." (PMID 37204309, 2023). "Our study also identified several other genes, such as ZNF827, MIR7641-2, RAPTOR, KSR1, GTF3C3, and NFIC, whose role in obesity or obesity-related disorders has been consistently shown in previous studies." (PMID 37204309, 2023).
lung carcinoma (3 papers, 2015 to 2025). "Indeed, KSR1 has been shown to contribute to oncogenesis in various forms of Ras-activated cancer, including skin, pancreatic and lung carcinomas." (PMID 26425651, 2015). "Moreover, depletion of KSR1 reduces tumor growth of K-Ras-dependent pancreatic and lung cancer xenografts in nude mice, further supporting KSR1 as an oncogene as well as a potential therapeutic target." (PMID 26425651, 2015).
melanoma (3 papers, 2022 to 2025). A malignant, usually aggressive tumor composed of atypical, neoplastic melanocytes. "In melanoma harboring the oncogenic BRAFV600E mutation, KSR1 knockout impaired cell proliferation, induced cell cycle arrest, and promoted apoptosis, highlighting a context-dependent synthetic vulnerability in BRAF-driven tumors." (PMID 41155983, 2025). "In several malignancies—including pancreatic ductal adenocarcinoma, melanoma, and skin carcinoma—KSR1 has been identified as an oncogenic facilitator of RAS/MAPK signaling, and its genetic or pharmacological inhibition suppresses tumor growth." (PMID 41155983, 2025). "In melanoma, KSR1 deletion impaired ERK phosphorylation, leading to reduced proliferation, invasion, and metastasis, along with increased senescence and apoptosis." (PMID 41155983, 2025). "The expression of the tumour suppressor protein PDCD4 (Programmed Cell Death 4) correlates with a good prognosis in melanoma and is upregulated in KSR1−/− cells." (PMID 37511580, 2023). "Knocking out KSR1 in the BRAFV600E-driven melanoma cell line SK-MEL-239 resulted in a complex phenotype that shows features of aberrant cell cycle regulation, enhanced senescence, and increased apoptosis." (PMID 37511580, 2023). "Thus, knocking down KSR1 by siRNA in two other BRAFV600E-driven melanoma cell lines results in the same key adaptations as observed in the KSR1−/− SK-MEL-239 cells." (PMID 37511580, 2023). "We used CRISPR/Cas9 to knock out KSR1 in a BRAFV600E-transformed melanoma cell line." (PMID 37511580, 2023). "Therefore, KSR1 was knocked out in BRAFV600E-driven melanoma cells." (PMID 37511580, 2023). "Notably, KSR2 has also been linked to MAPK pathway reactivation and resistance to BRAF+MEK inhibition in melanoma cells, thus suggesting that the roles of KSR1 or KSR2 in modulating the response to KRAS/MAPK pathway inhibition may have been underestimated." (PMID 35313064, 2022). "When KSR1 is lost, ERK activates the executioner Caspase 3 and inactivates the apoptosis antagonist BAG3 to promote apoptosis in our BRAFV600E-driven melanoma models." (PMID 37511580, 2023). "In order to corroborate the observed key changes in RAF-ERK signalling and senescence upon KSR1 depletion in other melanoma cell lines, BRAFV600E-driven melanoma cell lines SK-MEL-28 and A375 were transfected with KSR1 siRNA, and adaptations were analysed by Western blotting." (PMID 37511580, 2023).
Arthritis (2 papers, 2013 to 2014). Inflammation of a joint. "Their findings showed that the induction of arthritis is impaired in the absence of KSR1 and that this gene plays a role in ERK activation during inflammatory and stress responses both in vitro and in vivo." (PMID 24886659, 2014). "Furthermore, in the absence of KSR1, the induction of arthritis is impaired and KSR1 knockout mice have enlarged adipocytes, indicating a possible role of KSR1 in adipogenesis." (PMID 23455463, 2013).
COVID-19 (2 papers, 2025). A disease caused by infection with severe acute respiratory syndrome coronavirus 2. "The KSR1 gene is a protein that also contributes to immune function in several ways, including T-cell responses, immune homeostasis, and lung defense, processes that are critical in determining the severity of COVID-19." (PMID 41009975, 2025). "KSR1 levels in PLWH with COVID-19 were significantly lower than those in the HC group." (PMID 40568587, 2025).
glioma (2 papers, 2017 to 2019). A benign or malignant brain and spinal cord tumor that arises from glial cells (astrocytes, oligodendrocytes, ependymal cells). "Kinase suppressor of ras 1 (K-RAS), was indicated as a direct target of miR-199a, as well as expression levels of K-RAS were inversely correlated with expression levels of miR-199a in human glioma specimens." (PMID 31681604, 2019). "Interestingly, ectopic miR-34a was shown to sensitizecolorectal carcinoma cells to 5-fluorouracil; meanwhile,miR-497 reduces tumor cell proliferation and sensitizes to 5-fluorouracil by inactivating KSR1, and targets N-RAS to increase temozolomide-dependent apoptosis in gliomas." (PMID 27992364, 2017).
leukemia (2 papers, 2018 to 2022). A malignant (clonal) hematologic disorder, involving hematopoietic stem cells and characterized by the presence of primitive or atypical myeloid or lymphoid cells in the bone marrow and the blood. "Since basal expression of KSR1 (Kinase Suppressor of Ras 1) was reported in HL60 acute promyelocytic leukemia cells, a transcriptionally active KSR1 promoter might be expected in leukemia and drive de novo expression of TENM1, with potential functional consequences." (PMID 30618566, 2018). "Although TPL2 levels were found to be robustly increased in various CRC cell lines, this increase did not impact KSR1 protein levels unlike in leukemia cells." (PMID 35391917, 2022).